AGK (acylglycerol kinase)
Diseases named in the same sentence as AGK in open-access papers (continued):
Sharing a sentence is not in itself a finding about the gene and the disease.
breast carcinoma (continued). "Taken together, our results suggest that FOXO1 plays a critical role in the pro-proliferative effect of AGK on breast cancer cells." (PMID 24886245, 2014). "In this study, we found that AGK was markedly overexpressed in breast cancer cells and clinical tissue samples." (PMID 24886245, 2014). "Overexpressing AGK dramatically promoted the proliferation and tumorigenicity of breast cancer cell both in vitro and in vivo, whereas silencing AGK had the converse effect." (PMID 24886245, 2014). "Collectively, our results suggest that AGK promotes cell cycle G1/S transition in breast cancer cells." (PMID 24886245, 2014). "Collectively, these results indicate that AGK plays a significant role in the tumorigenicity of breast cancer cells both in vitro and in vivo." (PMID 24886245, 2014). "Taken together, our findings suggest that AGK functions as an oncoprotein during breast cancer progression." (PMID 24886245, 2014). "The clinical significance and biological role of AGK in breast cancer, however, remain to be established." (PMID 24886245, 2014). "The key findings presented in this study suggest that AGK is markedly upregulated in breast cancer cells and its ectopic expression promotes the proliferation and tumorigenicity of breast cancer cells both in vitro and in vivo." (PMID 24886245, 2014). "We also found that AGK expression inversely correlated with FOXO1 in the ten freshly collected clinical breast cancer samples (r = -0.721, P = 0.019)." (PMID 24886245, 2014). "Breast cancer patients with higher levels of AGK expression had shorter overall survival compared to patients with lower AGK levels." (PMID 24886245, 2014). "Consequently, it is evident that Netupitant mediates its anti-proliferative effects on breast cancer cells by targeting AGK and inhibiting the PI3K/AKT/mTOR signaling pathway." (PMID 39594764, 2024). "Our results have provided new insights into the role of AGK in the progression of human breast cancer, indicating that targeting AGK may offer a novel therapeutic strategy in the treatment of patients with breast cancer." (PMID 24886245, 2014). "Therefore, the role of AGK-modulation of GSK-3β activity in breast cancer cells is currently under investigation by our group." (PMID 24886245, 2014). "Furthermore, our results suggest a potential role for AGK as a clinical predictor of disease progression, prognosis and survival in patients with breast cancer." (PMID 24886245, 2014). "Consistently, IHC analysis indicated that AGK was markedly upregulated in breast cancer samples." (PMID 24886245, 2014). "Taken together, these findings provide new evidence that AGK plays an important role in promoting proliferation and tumorigenesis in human breast cancer and may serve as a novel prognostic biomarker and therapeutic target in this disease." (PMID 24886245, 2014). "In this study, we found that AGK expression was upregulated in a large cohort of human breast cancer tissues, and was significantly correlated with the clinicopathologic characteristics of breast cancer, including clinical stage and TNM classification." (PMID 24886245, 2014). "Therefore, our results support the proposal that AGK is a proliferation-promoting and oncogenic protein in breast cancer cells." (PMID 24886245, 2014). "AGK has been reported to be upregulated in various tumor types including prostate cancer, esophageal squamous cell carcinoma, ovarian cancer, gastric cancer and breast cancer." (PMID 25474138, 2014). "Herein, we report that AGK was markedly overexpressed in breast cancer cells and clinical tissues." (PMID 24886245, 2014). "Next, we investigated the effect of AGK on the tumorigenicity of breast cancer cells." (PMID 24886245, 2014). "AGK has been reported to be upregulated in various types of tumors including prostate cancer, esophageal squamous cell carcinoma, ovarian cancer, gastric cancer and breast cancer." (PMID 25474138, 2014).
breast carcinoma (continued). "Therefore, investigating whether there are already-approved drugs that target AGK for breast cancer treatment holds substantial value." (PMID 39594764, 2024). "Consequently, this study employed a structure-based drug screening strategy that integrates in vitro cell lines and subcutaneous tumor models in nude mice to identify potential marketed drugs targeting AGK, with the aim of providing survival benefits for breast cancer patients." (PMID 39594764, 2024). "Importantly, AGK has been identified as a key oncogene that is highly expressed in a range of tumor types, such as prostate cancer, breast cancer, cervical squamous cell carcinoma, and esophageal squamous cell carcinoma (ESCC)." (PMID 34368119, 2021). "Additionally, the increased tumorigenicity observed in response to AGK-mediated downregulation of FOXO1 in breast cancer may be due to aberrant activation of AKT, which is a major downstream effector of the EGFR." (PMID 26443540, 2016). "We gained valuable insights into the mechanism of AGK expression in breast cancer cells by demonstrating that overexpressing AGK significantly enhanced, whereas silencing endogenous AGK inhibited, the proliferation and tumorigenicity of breast cancer cells both in vitro and in vivo." (PMID 24886245, 2014). "However, the clinical significance and biological role of AGK in human breast cancer remain unclearly." (PMID 24886245, 2014). "AGK has been suggested to promote tumorigenesis in various cancers, including ESCC, hepatocellular cancer, and breast cancer." (PMID 26443540, 2016). "Establishing the precise role played by AGK in breast cancer progression will not only advance our understanding of the biology of breast cancer but may offer a mechanism for a novel therapeutic strategy via suppression of AGK expression in breast cancer cells." (PMID 24886245, 2014). "We showed that depletion of FOXO1 restored the growth rate of AGK-silenced breast cancer cells, indicating that FOXO1 plays a critical role in the pro-proliferative effect of AGK on breast cancer cells." (PMID 24886245, 2014). "Furthermore, survival analyses showed that patients with higher levels of AGK expression had shorter overall survival time compared to those with lower AGK expression, suggesting that AGK may represent a novel predictor for prognosis and survival in breast cancer." (PMID 24886245, 2014). "Additionally, AGK expression was positively correlated with STAT3 activation in lung cancer and breast cancer." (PMID 34368119, 2021).
lactic acidosis (10 papers, 2014 to 2025). Metabolic acidosis characterized by the accumulation of lactate in the body. "It is clinically characterized by congenital cataract, hypertrophic cardiomyopathy, mitochondrial myopathy, and lactic acidosis, and genetically by mutations in the acylglycerol kinase (AGK) gene." (PMID 36253788, 2022). "Autosomal recessive disorder caused by mutations in AGK encoding acylglycerol kinase, Clinical presentation: congenital cataracts, HCM, skeletal myopathy, exercise intolerance and lactic acidosis." (PMID 40678571, 2025). "The results of muscle biopsy, together with the presence of cataract, lactic acidosis and left ventricular hypertrophy, prompted us to analyze the AGK gene." (PMID 36253788, 2022).
cataract (7 papers, 2017 to 2023). Partial or complete opacity of the crystalline lens of one or both eyes that decreases visual acuity and eventually results in blindness. "Mutations in AGK have been associated also with milder phenotypes like cataracts." (PMID 34356047, 2021). "Mutations in AGK (encoded by the AGK gene) were firstly associated with myopathy, combined complex I, III and IV deficiency, bilateral cataracts, and severe mtDNA depletion in skeletal muscle." (PMID 34356047, 2021).
melanoma (7 papers, 2014 to 2026). A malignant, usually aggressive tumor composed of atypical, neoplastic melanocytes. "We used the cBioPortal tool to analyze the frequency of AGK mutation types in various malignant tumors and found that AGK mutations are the most common, amplification and deletion mutations are found in some cancers, and fusions are found only in melanoma and prostate cancer." (PMID 34368119, 2021). "As expected, based on published activity in BRAF fusion models, daily administration of tovorafenib at clinically relevant doses resulted in tumor regression in the AGK::BRAF fusion melanoma model." (PMID 40111124, 2025). "Tovorafenib resulted in tumor regression in an AGK::BRAF fusion melanoma patient-derived xenograft model in vivo, while exhibiting little antitumor activity in NF1-LOF tumor models." (PMID 40111124, 2025). "In this study, we investigated the function of AGK in macrophages using mice with specific deletion of AGK in macrophages in B16-F10 melanoma and LLC tumor models." (PMID 39816692, 2025). "To investigate the function of macrophage AGK, we subcutaneously inoculated B16-F10 melanoma cells into Agkfl/fl and AgkcKO mice." (PMID 39816692, 2025). "Another example would be the AGK::BRAF fusion which is the most common BRAF 5′ partner in melanoma and adult lung cancers and present in 19% of pediatric patients with thyroid gland papillary carcinoma." (PMID 40111124, 2025). "The impact of tovorafenib on in vivo antitumor activity was assessed in an AGK::BRAF fusion melanoma PDX model and in two NF1-LOF models, including an ERMS PDX and the MeWo melanoma xenograft." (PMID 40111124, 2025). "In a single-dose pharmacokinetic–pharmacodynamic (PK–PD) study, mice bearing AGK::BRAF fusion melanoma PDX tumors were orally administered tovorafenib at 17.5 or 25 mg/kg." (PMID 40111124, 2025). "In the experiments carried out the patient-derived AGK-BRAF expressing melanoma cell line demonstrated an increased sensitivity to sorafenib." (PMID 24422672, 2014). "Taken together, the preclinical efficacy in the AGK::BRAF fusion melanoma model, and the fact that tovorafenib has been approved for relapsed/refractory pLGGs, supports tissue agnostic activity for tovorafenib in tumors harboring BRAF fusions or rearrangements." (PMID 40111124, 2025). "In mice bearing melanoma PDX tumors harboring an AGK::BRAF fusion, tumor regression was observed in response to oral administration of tovorafenib for 14 days at dosage levels of 25 and 17.5 mg/kg daily assessed in two separate efficacy studies, respectively (respectively)." (PMID 40111124, 2025). "Several of these fusions, such as the mentioned AGK::BRAF, KIAA1549::BRAF, and MKRN1::BRAF, have been previously reported in melanoma and other solid tumors." (PMID 40737104, 2025).
prostate carcinoma (7 papers, 2014 to 2026). A carcinoma that arises from epithelial cells of the prostate gland. "AGK expression was significantly associated with the primary tumor Gleason grade and prostatic capsular invasion in prostate cancer." (PMID 26443540, 2016). "The level of AGK expression is significantly associated with the Gleason scores and capsular invasion of prostate cancer, the angiogenesis and tumour cell survival of hepatocellular cancer, and the sustained constitutive JAK2/STAT3 activation in oesophageal squamous cell carcinoma." (PMID 32827244, 2020). "AGK in prostate cancer cells increases the formation and secretion of LPA, which leads to the transactivation of EGFR and the activation of the downstream MAPK signaling pathway, resulting in the growth of cancer cells." (PMID 34368119, 2021). "Recently, AGK is reported to be overexpressed in prostate cancer and esophageal squamous cell carcinoma (ESCC)." (PMID 24886245, 2014). "Therefore, targeted inhibition of AGK may provide additional therapeutic benefits for patients with prostate cancer." (PMID 34368119, 2021). "Overexpression of AGK transactivates epidermal growth factor receptor (EGFR) and enhances the proliferation and migration of prostate cancer cells in vitro." (PMID 25474138, 2014). "Moreover, overexpression of AGK transactivates the epidermal growth factor receptor (EGFR) and increases prostate cancer cell migration in vitro." (PMID 26443540, 2016). "Interestingly, it has been reported that AGK overexpression promotes aggressiveness in prostate cancer cells through activation of EGFR, and that upregulation of AGK promotes the stem cell-like phenotype in ESCC by sustaining JAK2 activity." (PMID 24886245, 2014).
congenital cataracts (6 papers, 2021 to 2025). "Sengers Syndrome, linked to AGK gene variants, involves congenital cataracts, skeletal myopathy, exercise intolerance, HCM, and urinary 3-methylglutaconic aciduria." (PMID 40678571, 2025). "We describe the case of an infant carrying a novel homozygous AGK variant, c.518+1G>A, who was born with congenital cataracts, pielic ectasia, critical congenital dilated myocardiopathy, and hyperlactacidemia and died 20 h after birth." (PMID 34948281, 2021).
renal cell carcinoma (6 papers, 2020 to 2026). "For example, ZDHHC2-mediated palmitoylation of mitochondrial acylglycerol kinase (AGK) increases sunitinib resistance in renal cell carcinoma by activating the AKT–mTOR signaling pathway." (PMID 39563863, 2024). "Meanwhile, research shows that Acylglycerol kinase (AGK), a newly discovered lipid kinase, could increase the nuclear accumulation of β-catenin by activating the PI3K/AKT/GSK-3β signaling pathway in renal cell carcinoma (RCC) that further potentiates the activity of TCF/LEF transcription factor." (PMID 35186189, 2022).
Skeletal myopathy (6 papers, 2021 to 2025). "AGK and SLC25A4 variants often cause cardiac and skeletal myopathy frequently with mtDNA depletion." (PMID 38804971, 2024). "Furthermore, recessive AGK variants cause potentially fatal infantile respiratory and cardiac failure, but recessive SLC25A4 variants cause a childhood-onset intermediate form of cardiac and skeletal myopathy." (PMID 38804971, 2024).
esophageal squamous cell carcinoma (5 papers, 2014 to 2024). Esophageal squamous cell carcinoma (ESCC) is a type of esophageal carcinoma (EC) that can affect any part of the esophagus, but is usually located in the upper or middle third. "Consistent with our current findings, a previous study demonstrated that AGK was a significant factor that determined the patient response to chemoradiotherapy in esophageal squamous cell carcinoma." (PMID 25474138, 2014). "AGK was reported to be overexpressed in prostate, breast, esophageal squamous cell carcinoma (ESCC), and oral squamous cell carcinoma." (PMID 26443540, 2016). "In esophageal squamous cell carcinoma (ESCC), AGK directly binds to the Janus kinase homology 2 (JH2) domain of JAK2 to block the inhibition of JAK2 mediated by JH2, which leads to the activation of the JAK2/STAT3 signaling pathway and enhances the tumorigenicity of ESCC cells in vivo and in vitro." (PMID 34368119, 2021). "A previous study found that acylglycerol kinase overexpression augmented JAK2/STAT3 sustained activation, promoting tumorigenicity of esophageal squamous cell carcinoma (ESCC)." (PMID 38182570, 2024).
hepatocellular carcinoma (5 papers, 2014 to 2023). A malignant tumor that arises from hepatocytes. "AGK is reported to inhibit the apoptosis via activation of the NF-κB signaling in hepatocellular carcinoma." (PMID 35197069, 2022). "AGK expression also enhances hepatocellular cancer angiogenesis and inhibits tumour cell apoptosis through the activation of NF‐κB signalling." (PMID 32827244, 2020). "For instance, CUL4A mediates the ubiquitination of LATS1 to regulate YAP activity in hepatocellular carcinoma, AGK inhibits the activation of the Hippo pathway proteins in GC38 and CD44 functions upstream of the Hippo signalling pathway and attenuates its activation in glioblastoma." (PMID 37555915, 2023). "Data from a recent mouse model showed that the tumors formed by AGK-transduced hepatocellular carcinoma (HCC) cells grew more rapidly and were larger in size, while the tumors formed by AGK-silenced cells were smaller in both size and weight, compared to the tumors formed by control cells." (PMID 26443540, 2016).
gastric cancer (4 papers, 2014 to 2022). A primary or metastatic malignant neoplasm involving the stomach. "We also found that AGK expression was associated with tumour cell de‐differentiation and poor overall survival of gastric cancer patients." (PMID 32827244, 2020). "AGK expression was up‐regulated in gastric cancer and was associated with poor prognosis in gastric cancer patients." (PMID 32827244, 2020). "Therefore, in this study, we investigated the effects of AGK on gastric cancer cell proliferation and carcinogenesis and the underlying molecular events." (PMID 32827244, 2020). "Importantly, AGK expression was associated with the YAP1 expression in gastric cancer cells and tissues." (PMID 32827244, 2020). "To further confirm the role of YAP1 in the regulation of AGK in gastric cancer cells, we associated AGK expression with other YAP1‐related proteins in gastric cancer tissue samples and found that AGK expression was also associated with the expression of TEAD1, TEAD2 and TEAD4." (PMID 32827244, 2020). "Our current data indicate an association of AGK with YAP1 in gastric cancer; thus, we compared the expression of these proteins in 120 gastric cancer tissue samples and found that both YAP1 and AGK were significantly up‐regulated in tumour tissues, which is consistent with previous studies." (PMID 32827244, 2020). "There have been many research findings that AGK is overexpressed in many cancers, such as gastric cancer and cervical squamous cell cancer." (PMID 35280808, 2022). "AGK overexpression increased gastric cancer proliferation, invasion capacity and the expression of the epithelial‐mesenchymal transition markers in vitro." (PMID 32827244, 2020). "Our current study further demonstrated that the expression of YAP1/TEADs and the AGK protein was highly associated and that YAP1/TEADs can transcriptionally up‐regulate AGK expression in gastric cancer cells." (PMID 32827244, 2020). "In the current study, the AGK expression was analysed in the tissue samples of 120 cases of gastric cancer using immunohistochemistry." (PMID 32827244, 2020). "Taken together, these results suggest that AGK functions as an oncogene in these human cancers, including gastric cancer." (PMID 32827244, 2020). "Ectopic AGK expression induced gastric cancer cell proliferation and epithelial‐mesenchymal transition in vitro." (PMID 32827244, 2020). "In our current study, we found that the AGK protein was significantly up‐regulated in gastric cancer cell lines and tissue samples." (PMID 32827244, 2020). "Conversely, the knockdown of AGK expression reduced gastric cancer cell proliferation in vitro and in nude mouse tumour cell xenografts." (PMID 32827244, 2020). "Our own Western blot and immunohistochemistry data show that the expression of the AGK protein was higher in gastric cancer tissues than in the paired non‐cancerous tissues." (PMID 32827244, 2020). "Based on the expression levels of AGK in gastric cancer cell lines, BGC‐823 and HGC‐27 cells were chosen for overexpression and knockdown assays, respectively." (PMID 32827244, 2020). "Next, we determined the effect of AGK on the gastric cancer invasion capacity using a tumour cell invasion assay." (PMID 32827244, 2020). "This study investigated the effects of AGK on gastric cancer cell proliferation and carcinogenesis and explored the underlying molecular events." (PMID 32827244, 2020). "In conclusion, our current study provides the first evidence that AGK expression is up‐regulated in gastric cancer cells and tissues, and that the up‐regulation of AGK is associated with poor overall survival of gastric cancer patients." (PMID 32827244, 2020). "In gastric cancer, AGK is involved in tumor progression through the Hippo pathway." (PMID 34368119, 2021). "Therefore, targeting the expression or activity of AGK seems to be a therapeutic target to control the progression of gastric cancer." (PMID 34368119, 2021).